H19 (H19 imprinted maternally expressed transcript)
Diseases named in the same sentence as H19 in open-access papers (continued):
Sharing a sentence is not in itself a finding about the gene and the disease.
primary biliary cholangitis (5 papers, 2020 to 2025). Primary biliary cholangitis (PBC) is a chronic and slowly progressive cholestatic liver disease of autoimmune etiology characterized by injury of the intrahepatic bile ducts that may eventually lead to liver failure. "H19 was markedly upregulated in primary sclerosing cholangitis and primary biliary cirrhosis, which prevented zinc finger E‐box binding homeobox 1 (ZEB1) inhibition of epithelial cell adhesion molecule (EpCAM), causing EpCAM activation and contributing to biliary hyperplasia." (PMID 37398637, 2023). "For instance, cholangiocyte-derived exosomal lncRNA H19 is closely correlated with macrophage activation and hepatic fibrosis in BDL cholestatic mouse models, as well as in human primary sclerosing cholangitis (PSC) and primary biliary cholangitis (PBC) patients." (PMID 41479922, 2025).
temporal lobe epilepsy (5 papers, 2018 to 2022). A localization-related (focal) form of epilepsy characterized by recurrent seizures that arise from foci within the temporal lobe, most commonly from its mesial aspect. "It was consistent with the previous data that H19 contributes to glial cell activation and apoptosis of hippocampal neurons in the brain of temporal lobe epilepsy." (PMID 35603469, 2022). "In temporal lobe epilepsy, lncRNA H19 was pronouncedly different from normal individuals, and it was overexpressed." (PMID 33708438, 2021). "Together, lncRNA H19 could competitively bind let‐7b to promote hippocampal glial cell activation and epileptic seizures by targeting Stat3 in a rat model of temporal lobe epilepsy." (PMID 32648622, 2020). "LncRNA H19 could competitively bind to let‐7b to promote hippocampal glial cell activation and epileptic seizures by targeting Stat3 in a rat model of temporal lobe epilepsy." (PMID 32648622, 2020). "Additionally, previous study reported that lncRNA H19 was overexpressed in the rat model of temporal lobe epilepsy, and its downstream targets were predicted to be related to immune and inflammatory responses and neuronal apotosis by function and pathway analysis." (PMID 35603469, 2022).
urothelial cell carcinoma (5 papers, 2010 to 2021). "Another study suggested that in urothelial cell carcinoma individuals, both H19 SNPs rs2107425 and rs217727 polymorphic variants were susceptible to increased risks of muscle invasive tumors." (PMID 32337223, 2020). "H19 and IGF2-P4 gene expression was tested in samples of Transitional Cell Carcinoma (TCC) of the bladder by in-situ hybridization (ISH) and by quantitative Real-Time PCR (qRT-PCR)." (PMID 21162716, 2010).
acute promyelocytic leukemia (4 papers, 2018 to 2024). An aggressive form of acute myeloid leukemia (AML), characterized by arrest of leukocyte differentiation at the promyelocyte stage, due to a specific chromosomal translocation t(15;17) in myeloid cells. "Besides, H19 impedes the function of telomerase, which extends the length of telomeres, in human acute promyelocytic leukemia cells." (PMID 35892588, 2022). "In in vitro studies done on the NB4 cell line (acute promyelocytic leukemia (APL) -AML-M3 cell line), ATRA (all-trans retinoic acid) induces overexpression of H19 and causes the decrease of telomerase activity necessary for tumor growth." (PMID 36362925, 2022).
adrenocortical carcinomas (4 papers, 2012 to 2022). "Reciprocal regulation of IGF-2 and H19 expression is seen in adrenocortical carcinoma, where H19 suppression by promoter methylation is associated with increased IGF-2 expression and cell proliferation." (PMID 35597813, 2022). "The abnormal methylation at the IGF2/H19 locus is common in adrenocortical carcinomas and methylation patterns of IGF2 regulatory regions has been proposed to discriminate ACC from adrenal adenomas with high diagnostic accuracy." (PMID 33260476, 2020). "Liu's study showed that H19 expression is maintained at low levels in hormonally active adrenocortical carcinomas, which is consistent with our study." (PMID 31156552, 2019). "Altered DNA methylation of the H19 promoter has been shown to be involved in the abnormal expression of both H19 and IGF-2 genes in adrenocortical carcinomas." (PMID 24832650, 2012).
Aortic dissection (4 papers, 2021 to 2025). Aortic dissection refers to a tear in the intimal layer of the aorta causing a separation between the intima and the medial layers of the aorta. "Conversely, the described effects were reversed after inhibition of H19 expression, whereby substantial evidence supports that H19 may be involved in the development of aortic dissection." (PMID 37896804, 2023). "We speculated that it plays an important role in arterial disease, and therefore studied the role and mechanism of H19 in aortic dissection (AD)." (PMID 33403385, 2021).
autoimmune disease (4 papers, 2017 to 2025). A disorder resulting from loss of function or tissue destruction of an organ or multiple organs, arising from humoral or cellular immune responses of the individual to their own tissue constituents. "Hypomethylation of the ICR leads to higher H19 transcription, which in autoimmune diseases may increase lymphocyte activation and worsen damage to the glandular epithelium." (PMID 41301757, 2025). "In contrast to cancer biology, the role of H19 in IBD and other inflammatory or autoimmune diseases has been scarcely studied." (PMID 37716920, 2023).
calcific aortic valve disease (4 papers, 2018 to 2021). "During calcific aortic valve disease, DNA methylation in the H19 promoter is dysregulated, causing H19 to interfere with the expression of NOTCH1 to promote the osteogenesis process in the aortic valve." (PMID 34583640, 2021). "Epigenetic dysregulation of long noncoding RNA H19 was recently found to be associated with calcific aortic valve disease (CAVD) in humans by repressing NOTCH1 transcription." (PMID 31609547, 2019). "The decrease in DNA methylation in the promoter region of lncRNA H19 also was associated with calcific aortic valve disease (CAVD)." (PMID 30003100, 2018). "For calcific aortic valve disease, a dysregulation of DNA methylation in the H19 promoter stimulates a more osteogenic phenotype by interfering with NOTCH1 expression." (PMID 34103071, 2021).
cerebral infarction (4 papers, 2019 to 2024). An ischemic condition of the brain, producing a persistent focal neurological deficit in the area of distribution of the cerebral arteries. "TTC staining revealed a significantly larger volume of cerebral infarction in the I/R + sh‐H19 + sh‐IMP2 group than in the I/R + sh‐H19 group (p < 0.01)." (PMID 39161158, 2024). "TTC staining demonstrated a significant decrease in brain infarction volume due to H19 knockdown relative to the observations in the I/R + sh‐NC group on day 7 post‐cerebral I/R (p < 0.01)." (PMID 39161158, 2024). "Also, the inhibition of H19 in ischemic rats significantly decreased brain infarct size, neurological deficit, and neuronal apoptosis." (PMID 33541284, 2021).
diabetic foot ulcers (4 papers, 2020 to 2024). "For example, H19 derived from MSC exosomes was transferred from MSCs to fibroblasts, thereby inhibiting fibroblast apoptosis and inflammation and activating the wound healing process in diabetic foot ulcers." (PMID 34368161, 2021).
head and neck carcinoma (4 papers, 2015 to 2024). A carcinoma that arises from the head and neck region. "In head and neck cancers, numerous studies have shown that H19 was elevated, such as in tongue or laryngeal squamous cell carcinomas." (PMID 33672311, 2021). "Several recent studies have reported that multiple lncRNAs are involved in the progression of head and neck cancer; for example, H19, NEAT1, and HOTAIR are overexpressed in laryngeal cancer." (PMID 32039035, 2019). "Finally, H19 LOI has been found to be present in patients with head and neck carcinoma, and patients with high expression of H19 appeared to be more likely to experience relapse." (PMID 38812777, 2024).
hypertrophic cardiomyopathy (4 papers, 2021 to 2025). A condition in which the myocardium is hypertrophied without an obvious cause. "Their study established a statistically significant link between H19 variants and an increased risk of developing hypertrophic cardiomyopathy." (PMID 34502285, 2021). "Some researchers identified H19 variants in a group of patients with hypertrophic cardiomyopathy and compared their allele and genotype frequencies to those of healthy controls." (PMID 34502285, 2021).
insulinomas (4 papers, 2012 to 2020). "However, H19 also contains let-7 binding sites and over-expression of a H19 variant without these binding sites (H19Δ) did not cause β-cell proliferation in adult dissociated islet cells or rat insulinoma cells." (PMID 30551650, 2018). "This possibility would be reminiscent to some human pancreatic tumors like insulinomas where Igf2 DMR2 is hypermethylated while the H19 ICR is monoallelically methylated and where Igf2 becomes also expressed from the unmethylated maternal allele (loss of imprinting)." (PMID 22662250, 2012). "Conversely, the significantly opposite methylation and expression changes exemplified by LSP1, H19, TH, KCNQ1, SLC22A18, OSBPL5 are thus more likely random and unrelated to insulinoma pathogenesis." (PMID 33060578, 2020). "Parenthetically, the two ICRs in this region, the H19/IGF2 ICR (chr11: 2,018,812–2,024,740) and KvDMR1 (chr11: 2,719,948–2,722-259), each displayed approximately equal percent methylation in beta cells (49.5% and 41.9%, respectively) and insulinomas (47.9% and 36.5%, respectively)." (PMID 33060578, 2020).
ischemia (4 papers, 2022 to 2025). A hypoperfusion of the BLOOD through an organ or tissue caused by a PATHOLOGIC CONSTRICTION or obstruction of its BLOOD VESSELS, or an absence of BLOOD CIRCULATION. "Interestingly, using CRISPR-Cas9 genome editing, knocking out H19 in NSCs inhibited cellular proliferation as well as neuronal differentiation and survival, resulting in worsening of motor and cognitive deficits post-ischemia." (PMID 35946958, 2022). "While no hind-limb ischemia studies have been performed on p21–/– or p16–/– mouse models, knockdown of the lncRNA H19 has been shown to affect senescence with increased p16 and p21 expression and decreased cellular proliferation, leading to the accumulation of cells in G0/G1 phase." (PMID 34793334, 2022).
lymphoma (4 papers, 2015 to 2024). A malignant (clonal) proliferation of B- lymphocytes or T- lymphocytes which involves the lymph nodes, bone marrow and/or extranodal sites. "Noteworthy, loss of imprinting of H19, resulting in high H19 expression, was described in adult T-cell leukemia/lymphoma patients and cell lines, suggesting that H19 might play different roles in distinct hematological tumors." (PMID 27177333, 2016). "It suggested that EBV induced LOI of H19 in malignant lymphoma." (PMID 35674441, 2022). "Allele-specific expression of H19 in EBV-positive GC, NPC, and lymphoma tissues." (PMID 35674441, 2022). "Therefore, EBV may promote the carcinogenic process of malignant lymphoma via regulating H19 expression and the exact mechanism remains to be revealed." (PMID 35674441, 2022).
Miscarriage (4 papers, 2019 to 2024). A pregnancy that ends at a stage in which the fetus is incapable of surviving on its own, defined as the spontaneous loss of a fetus before the 22th week of pregnancy. "In the embryonic chorion tissue of spontaneous abortion (SA), the expressions of H19 and ITGB3 at both the mRNA and protein levels decreased." (PMID 30780128, 2019). "In addition, a microarray analysis showed lowered levels of H19 in the villous tissues from idiopathic recurrent miscarriage patients." (PMID 39026605, 2024). "In addition, a microarray analysis using 12 abortion and 12 miscarriage samples showed that H19 expression levels were significantly lower in miscarriage samples." (PMID 35954272, 2022).
non-alcoholic fatty liver disease (4 papers, 2019 to 2021). "In nonalcoholic fatty liver disease, lnc-H19 and lnc-Malat1 jointly mediate the stability of SREBP1c." (PMID 34597331, 2021). "Recently, H19 was reported to modulate hepatic metabolic homeostasis in non-alcoholic fatty liver disease (NAFLD)." (PMID 34179148, 2021). "We therefore tested the levels of H19 and miR-675 expression in human cirrhotic livers and compared it with non-alcoholic fatty liver disease (NAFLD) livers." (PMID 33499244, 2021).
Parkinson disease (4 papers, 2008 to 2021). A progressive degenerative disorder of the central nervous system characterized by loss of dopamine producing neurons in the substantia nigra and the presence of Lewy bodies in the substantia nigra and locus coeruleus. "LncRNA H19 regulates miR-585-3p/PIK3R3 to attenuate MPTP-induced apoptosis in Parkinson's disease." (PMID 34238324, 2021). "We also examined expression of H19, IGF2, and CDKN1C in laser-captured dopamine neurons, identified on the basis of neuromelanin presence, from a series of human postmortem RNA samples from human cases of Parkinson's disease and controls." (PMID 18183302, 2008).
polycystic ovary syndrome (4 papers, 2020 to 2023). A disorder that manifests as multiple cysts on the ovaries. "A recent study provided the first evidence that the lncRNA H19 is associated with polycystic ovary syndrome (PCOS) in women and that increased levels of lncRNA H19 are a risk factor for PCOS." (PMID 35725373, 2022). "Conversely, excess H19 may have an impact on the development of PCOS-related hyperandrogenemia." (PMID 37507391, 2023).
Prostate Tumor (4 papers, 2018 to 2024). "Similarly, PIM1‐mediated H19 induction was also observed in normal human prostate‐derived epithelial cells, hPrEC, or prostate tumor cell line PC3." (PMID 32146726, 2020). "On the basis of these preliminary data, we hypothesize that lower levels of basal H19 may be associated with the presence of both hypoxic area and estrogens stimuli in prostatic tumors that, in turn, mediate an H19-dependent beta integrin subunit induction." (PMID 31426484, 2019). "Next, we characterize at the molecular level prostate tumors at the time of biopsies evaluating, as novel prognostic biomarkers, eNOS, HIF-2α, and β4 integrin by immunohistochemistry (IHC) and, in parallel, H19 and CDH1 RNA levels by ddPCR." (PMID 39457633, 2024).
rectal cancer (4 papers, 2018 to 2026). A primary or metastatic malignant neoplasm that affects the rectum. "H19 serves as a precursor for miR-675, and its elevated expression correlates with an upsurge in miR-675 levels, contributing to rectal cancer progression." (PMID 40129920, 2025). "Low HDAC2 expression promotes EMT and rectal cancer metastasis by upregulating H19/MMP14." (PMID 37631010, 2023). "H19, the first identified lncRNA overexpressed in HCC and rectal cancer, influences cancer development." (PMID 40129920, 2025). "A microarray analysis indicated the RNA expression of five genes (NDRG1, ERRFI1, H19, MPZL3, and UCA1) was highly increased in radio-resistant rectal cancer cell lines." (PMID 29801473, 2018).
retinal ischemia (4 papers, 2020 to 2024). A ischemic disease that involves the retina. "Retinal ischemia–reperfusion injury is closely associated with DR progression, and studies have shown that retinal ischemia–reperfusion injury leads to the occurrence of retinal microglia focal death associated with lncRNA H19." (PMID 37443131, 2023). "In retinal ischemia-reperfusion, lncRNA H19/miR-21/PDCD4 axis can directly adjust microglia relaxation and neuron damage caused by I/R." (PMID 34180760, 2021).
status epilepticus (4 papers, 2018 to 2022). Status epilepticus is defined as a continuous seizure lasting more than 30 min, or two or more seizures without full recovery of consciousness between any of them. "Overexpression of H19 exacerbates status epilepticus (SE)-induced neuronal apoptosis in the hippocampus, whereas inhibition of H19 protects rats from SE-induced cellular damage." (PMID 36364766, 2022). "H19 was increased in rat hippocampus neurons after status epilepticus, which might be due to epileptic seizure‐induced hypoxia." (PMID 32648622, 2020). "H19 overexpression induced the activation of astrocytes and microglia and the release of proinflammatory cytokines (interleukin-1β and interleukin-6 and tumor necrosis factor-α) in the hippocampus, whereas H19 knockdown inhibited status epilepticus-induced glial cell activation." (PMID 29636074, 2018).
teratocarcinoma (4 papers, 2011 to 2021). A germ cell tumor characterized by the presence of an embryonal carcinoma component and a teratoma component. "Secondly, a mouse teratocarcinoma model demonstrated larger tumor growth when the embryo lacked H19, and finally in a hepatocarcinoma model, mice developed cancer much earlier when H19 was absent." (PMID 21489289, 2011). "Accordingly, in the absence of H19, induced teratocarcinomas were larger and the number of polyps found in APC mutant mice was more than twice higher than in the same tumor models expressing H19." (PMID 25861629, 2015).
Ureteral obstruction (4 papers, 2016 to 2022). Obstruction of the flow of urine through the ureter. "However, H19 seems to be differently regulated by IRI and unilateral ureteral obstruction as it was downregulated in the IRI-injured kidneys." (PMID 34697716, 2022).
acute lymphoblastic leukemia (3 papers, 2013 to 2023). Leukemia with an acute onset, characterized by the presence of lymphoblasts in the bone marrow and the peripheral blood. "The expression of H19 is up-regulated in AML compared to acute lymphoblastic leukemia (ALL)." (PMID 24312125, 2013). "We demonstrate that the PIM1 protein kinase induces the long noncoding RNA (lncRNA) H19 expression and promotes induction of a stem cell signature in both T‐cell acute lymphoblastic leukemia (T‐ALL) and PCa cells." (PMID 32146726, 2020). "However, the expressionlevel of H19 in acute lymphoblastic leukemia (ALL) has not been elucidated yet." (PMID 36680478, 2023).
adrenocortical tumor (3 papers, 2012 to 2015). "IGF2 overexpression has previously been associated with LOH at the IGF2/H19 locus in adrenocortical tumor samples." (PMID 26400872, 2015).
Alzheimer disease (3 papers, 2020 to 2024). A progressive, neurodegenerative disease characterized by loss of function and death of nerve cells in several areas of the brain leading to loss of cognitive function such as memory and language. "SLC35A4 is related to epileptic encephalopathy, while H19, ADORA2A and INPP5D are linked to cognitive impairment and Alzheimer's disease." (PMID 39020437, 2024).